CD1A (CD1a molecule)
Diseases named in the same sentence as CD1A in open-access papers (continued):
Sharing a sentence is not in itself a finding about the gene and the disease.
melanoma (25 papers, 2010 to 2025). A malignant, usually aggressive tumor composed of atypical, neoplastic melanocytes. "Several studies have investigated the association between CD1a-DCs infiltration into LNs and into the primary lesion of various organs, such as the breast, skin (melanoma), larynx, oral cavity, stomach and the uterus using various experimental approaches." (PMID 39684473, 2024). "The Breslow depth has been found to be associated with progressive migration of CD1a+ DC subsets in early melanoma." (PMID 34805163, 2021). "In human melanoma patients, lymph node metastases are associated with the suppression of the CD1a+ DC subset, a cellular population that is efficient at cross-presenting neoantigens to CD8+ T cells." (PMID 34439160, 2021). "In melanoma SLNs, CD1a+ LCs were proven to express molecules associated with mature phenotype." (PMID 35955602, 2022). "Consistent with this, supernatants from metastasis-derived melanoma cells were significantly more effective in down-regulating CD1a on moDCs in an IL-10-dependent fashion in comparison to primary melanoma cultures." (PMID 32507967, 2020). "This includes an antigen-presenting gene (CD1A), where 5’UTR mutations correlate significantly with decreased survival in melanoma." (PMID 28362259, 2017). "It has also been reported that infiltration of CD1a-positive DC within tumor cell nests and peritumoral area correlates with decreased tumor thickness and the radial growth phase of melanomas, respectively." (PMID 28331853, 2017). "Microscopic findings and the presence of histiocytic cells led to the performance of an immunohistochemical staining panel using monoclonal antibodies for S-100, CD1a, pan-cytokeratin, CD-68, melanoma marker (HMB45) and melanoma A protein." (PMID 26749317, 2016). "CD1a(+) DCs were found infiltrating both melanoma cell nests and the surrounding stroma, while DC-LAMP(+) mature DCs were generally confined to the peritumoral areas, associated with lymphocytic infiltrates." (PMID 32309563, 2015). "Langerhans cells (LC) (CD1a+ Langerin+), specific DCs, are major cells in skin’s immune system and subject of intense research in melanoma." (PMID 32309563, 2015). "Through flow cytometric analysis of tumor‐free lymph nodes draining the primary tumor site in melanoma patients, we and others identified both CD1a+ dermal DC (DDC) and LC subsets, migrated from the skin, and CD1a− LNR‐cDC subsets, derived from blood‐borne precursors." (PMID 39668411, 2025). "Interestingly, also in human melanoma lesions, CD1a expression on DCs was reported to be decreased in metastatic lesions as compared to primary lesions, which coincided with IL-10 expression specifically in metastatic lesions." (PMID 32507967, 2020). "Beside monocytes, fully differentiated DC can be recruited to the tumor microenvironment, where they may lose their characteristic CD1a expression through the suppressive action of IL-10, as shown for melanoma metastases." (PMID 24324467, 2013). "Monoclonal antibodies for S-100, CD1a pan-cytokeratin, CD-68, melanoma marker (HMB45) and melanoma A protein were included in this panel." (PMID 26749317, 2016). "DC density was associated with activated (CD25(+) / OX40(+)) T lymphocytes while infiltration of CD1a(+) and DC-LAMP(+) DCs were negatively correlated with melanoma’s thickness." (PMID 32309563, 2015). "In melanoma, CD1a-DCs numbers were significantly lower in non-sentinel LNs compared to sentinel LNs and the frequencies of CD1a-DCs subsets in sentinel LNs, assessed by flow cytometry, were related to local recurrence." (PMID 39684473, 2024). "Then, we determined their cellular origin (melanoma cells or immune cells, as T and B lymphocytes, monocytes and dendritic cells) by measuring the percentage of EVs positive for CD146, CD8, CD19, CD14 and CD1a, respectively." (PMID 35042524, 2022).
melanoma (continued). "Cluster differentiation 68 (CD68) and CD163 were positive and S100, CD1a, langerin, human melanoma black 45 (HMB-45) and Melan-A were negative in immunohistochemical staining." (PMID 32532290, 2020). "Recently, presence of CD1a-positive DCs around the tumor cell nests was also observed to correlate with the absence of hematogenous spread in malignant melanoma of the skin." (PMID 28331853, 2017). "We have identified and characterized four conventional DC subsets in melanoma SLN, two of which were positively identified as skin-derived CD1a+LC and DDC, and the remaining two (CD1a−CD14− and CD1a−CD14+) as LN-resident subsets with varying levels of BDCA3 and DC-SIGN expression." (PMID 24324467, 2013). "The pertinent negative markers include histiocytic markers (CD163, CD14, CD1a, langerin), FDC markers (CD21, CD23, CD35, clusterin, CXCL13), hematolymphoid markers (CD45, CD3, CD20, CD79a), vascular markers (CD31, CD34), melanoma markers (melanA, SOX10, HMB45, S100), and others (ALK, CD30)." (PMID 40563703, 2025). "The tumor cells were positive for CD68, S100, CD4 and lymphocyte common antigen, while epithelial membrane antigen, HMB-45, CK AE1/AE3, myogenin, desmin, CD1a, CD21 and SALL-4 were negative thus ruling out rhabdomyosarcoma, extrarenal rhabdoid tumor, Langerhans cell sarcoma and malignant melanoma." (PMID 31890359, 2019). "Based on our analysis, the prototype of the intratumor inflammatory infiltrate in a melanoma with good prognosis is composed of numerous T cells CD3+, few or even absent B cells CD20+, few or absent plasma cells CD138+, and present Langerhans cells CD1a+ or langerin+." (PMID 24163809, 2013).
breast carcinoma (20 papers, 1999 to 2026). "Regarding other prognostic indicators in breast cancer, we noted that higher numbers of CD1a+ DCs in lymphoid tissue were associated with a lower tumor histological grade and HER2 negativity." (PMID 35955602, 2022). "The finding of paucity of CD1a+ cells in many of the breast carcinomas examined indicated that DC mediated co-stimulation of T-lymphocytes in many breast cancers is likely to be severely deficient." (PMID 11870535, 2002). "In breast cancer, a number of studies have reported that the degree of CD1a-DCs infiltration into LNs was similar in metastatic LNs and non-metastatic LNs and that CD1a-DCs infiltration into LNs had no significant impact on prognosis." (PMID 39684473, 2024). "CD1A-positive dendritic cell infiltration is associated with favorable prognosis in patients with CRC, esophageal carcinoma, and breast cancer." (PMID 38025525, 2023). "CD1a+ DCs have been reported to be present within breast cancers from early, preinvasive ductal carcinoma in situ to invasive ductal carcinomas." (PMID 33919875, 2021). "Coventry and Morton showed lower mortality rate of patients with breast cancer presenting with higher CD1a+ DC density within the tumour." (PMID 33919875, 2021). "The aim of this study was to assess the relationship between CD1a DC density in fresh human breast cancer tissues, with disease-specific 5-year postsurgery survival." (PMID 12888826, 2003). "On the other hand, S-100-positive DC do appear to show some correlation with the breast tumour grade, indicating that CD1a and S-100 define somewhat different populations of DCs in breast cancers." (PMID 12888826, 2003). "A total of 48 breast cancer patients were followed from the time of surgery and CD1a density analysis for 5 years or until death." (PMID 12888826, 2003). "CD1a-positive DCs have been reported to be present within breast cancers from very early, preinvasive DCIS lesions to invasive ductal carcinomas, but there was no statistical correlation between DC density and the grade of the tumour." (PMID 12888826, 2003). "The findings of the present study imply that many breast cancers not only fail to recruit DC but fail to drive DC into either the antigen capture/processing phase (CD1a+) or the antigen presentation/co-stimulatory phase (CMRF-44/56+)." (PMID 11870535, 2002). "Recent studies have demonstrated a low number of CD1a positive cells in human breast carcinomas and these have been able to be extracted using specific dissaggregation techniques." (PMID 11870535, 2002). "In 40 out of 48 breast cancers, CD1a-positive cells were detectable using these methods." (PMID 12888826, 2003). "Low CD1a-positive putative dendritic cell numbers in human breast cancer has recently been described and may explain the apparent ‘poor immunogenicity’ previously reported in breast cancer." (PMID 11870535, 2002). "It is likely that CD1a+cells have a role in antigen capture and presentation in human tumours, and this study documents the density of CD1a+cells in a large sample of all histological grades of human breast carcinomas." (PMID 10070894, 1999). "The finding that activation was low or absent in tumour-associated DC populations in most breast cancers may have some bearing on the lack of apparent statistical association between CD1a and S-100 expression and survival." (PMID 12888826, 2003). "This study aimed to investigate the density of DCs expressing CD1a, CD83, CD123, DC-LAMP3 (CD208) and DC-SIGN (CD209) in breast cancer." (PMID 33919875, 2021). "The aim of the present study was to investigate the density of DCs expressing CD1a, CD83, CD123, DC-LAMP3 (CD208) and DC-SIGN (CD209) in breast cancers." (PMID 33919875, 2021). "We used CD1a as a marker of immature DCs, CD83 as a marker for mature DCs, CD3 as a marker for T cells, and pan-cytokeratins as a marker for breast cancer cells." (PMID 24088396, 2013).
breast carcinoma (continued). "Recent studies of breast cancer tissue samples demonstrated that CX3CL1 expression correlates with increased anti-tumor immune cells, including CD8+ T cells, NK cells and Cd1a+ dendritic cells, which correlated with better patient prognosis." (PMID 23029290, 2012). "We have therefore examined CD1a expression as a marker for dendritic cells, together with CMRF-44 and -56 as markers of dendritic cell activation status, in 40 human breast cancers." (PMID 11870535, 2002). "This study investigates the expression of the epithelial DC marker CD1a with that of CMRF-44, CMRF-56 and CD83 to determine the activation state of DC in human breast cancer." (PMID 11870535, 2002). "Indeed, the profile of immune cells in the axillary TdLNs is known to provide prognostic value for breast cancer patients, with increased CD4+ T cells and CD1a+ DCs correlating with higher rates of disease-free survival." (PMID 39703517, 2024). "The lower proportion of mature DC-LAMP+/immature CD1a+ cells in positive breast carcinoma SLNs as compared with negative ones suggested that the maturation of DCs is arrested." (PMID 35955602, 2022). "Although we did not make such observations, we noted that breast cancer metastases of lobular histology are more abundantly infiltrated by CD1a+ DCs than NOS cancers." (PMID 35955602, 2022). "There has been no previous study evaluating the effects of CD1a + in dendritic cells in the context of breast cancer survival (in patients receiving neoadjuvant chemotherapy)." (PMID 33138797, 2020). "Although the presence of TIDCs has been documented to be associated with a better clinical outcome in a number of human solid cancers, this is not the case with CD1a+ TIDCs in breast cancer." (PMID 28913366, 2017). "Until recently, no study has specifically addressed the relationship of CD1a density in breast cancer to clinical outcome or survival." (PMID 12888826, 2003). "Taken collectively, these findings imply that the density of DC per se, as measured by CD1a or S-100, does not appear to act as an independent determinant of overall 5-year survival from breast carcinoma." (PMID 12888826, 2003). "We have previously shown that DCs are absent, or only present in very low numbers, in most human breast cancers using CD1a and other markers and that DCs are poorly activated." (PMID 12888826, 2003). "Two significant genes (CD1a and FCER1A) related with the survival outcome in the pCR prediction model have been reported as conventional dendritic cell markers and are highly expressed in innate antigen-presenting cells infiltrating breast cancer tissues, which is consistent with our findings." (PMID 33138797, 2020). "As reported for breast cancer, no influence of CD1a+ immature mDC on DSS was found." (PMID 25470820, 2014). "These are important findings and indicate that either (i) DC density may not directly determine tumour cell growth, metastasis and outcome in breast cancer or (ii) CD1a and S-100 as conventional measures of DC density may not be sensitive or specific enough for prognostic use." (PMID 12888826, 2003). "In a prior study, our group found significant decreases in immune cell populations within breast cancer non-sentinel lymph nodes (NSLNs), specifically in CD4+ T cells and CD1a+ DCs, and discovered that these changes strongly correlated with clinical outcome." (PMID 24088396, 2013). "In breast cancer, the number of CD83+ mature DCs, but not the number of CD1a+ or S100+ DCs, has been shown to be of prognostic relevance." (PMID 20969772, 2010). "Similarly, in a study examining the role of DC maturation status in patients with breast cancer, CD83 expression was prognostic for overall and relapse free survival whereas CD1a, a marker of immature DC, was not." (PMID 29872507, 2018). "In breast cancer, mature DCs detected by the CD83 or DC-LAMP marker were present in lower amount in tumor-positive SLNs compared to tumor-negative ones while the density of DCs stained for CD1a was similar." (PMID 23418928, 2013).
Erdheim-Chester disease (14 papers, 2016 to 2026). "Erdheim-Chester disease (ECD) is a rare multisystemic disease characterized by the infiltration of multiple organs by foamy CD68 + CD1a-histiocytes." (PMID 38669404, 2024). "Additionally, she had a pineal gland tumor, a biopsy from which revealed xanthogranulomatous infiltration with foamy histiocytes which were CD 68 positive and CD1a negative, diagnostic of Erdheim Chester disease." (PMID 41659134, 2025). "Additionally BRAFV600E mutation was also detected in other two rare histiocytoses: Langerhans-cell histiocytosis (LCH) and Erdheim-Chester disease (ECD) characterized by a phenotype similar to CD1a+ S100+ Langerhans cells and foamy CD68+, CD1a- S100- histiocytes, respectively." (PMID 27738305, 2017). "Erdheim-Chester disease (ECD) is a rare non-Langerhans cell histiocytosis caused by the expression of CD68-positive and CD1a-negative foam tissue cells, which is polar in pediatric patients." (PMID 35494046, 2022). "Erdheim-Chester disease (ECD) is a rare histiocytic disorder characterized by the infiltration of tissues with foamy, xanthomatous CD68/CD163-positive, CD1a-negative histiocytosis." (PMID 41994452, 2026). "Pathology of Non-Langerhans histiocytosis such as Erdheim-Chester disease involves characteristic Touton giant cells that are CD68 positive and CD1a negative." (PMID 35418930, 2022). "Diagnosis was suggested by xanthomatous skin lesions and a biopsy was compatible with Erdheim-Chester disease demonstrating xanthogranulomas CD68 positive (clone KP1) and CD1a and S100 negative." (PMID 33602153, 2021). "Although S-100 positive cells can be found in Erdheim-Chester disease (ECD) and Rosai-Dorfman disease, CD1a is always negative in the same histiocytes." (PMID 27760550, 2016). "Erdheim-Chester disease, on the other hand, is positive for CD68 and CD163, may express factor XIIIa, and is negative for langerin and CD1a; S100 may also be expressed." (PMID 40398847, 2025).
Histiocytosis (13 papers, 2009 to 2026). An excessive number of histiocytes (tissue macrophages). "Although we did not detect Birbeck's granules on electron microscopic study, an arrangement of histiocytosis in loose mesh-works or clusters and immunoreactivity for S-100 and CD1a antigens are helpful for a diagnosis of LCH." (PMID 19396700, 2009). "It was found that the stromal-like cells found in tissues affected by histiocytosis shared the phenotype characteristic for Langerhans cells (LCs), i.e. expression of langerin (CD207) and CD1a molecule." (PMID 38342891, 2024). "It is also important to exclude other histiocytosis, including LCH both by morphology and CD1a/Langerin immunostains and RDD by morphology of large RDD histiocytes (with and without emperipolesis) with diffuse, dark S100/fascin immunostains." (PMID 31685033, 2019). "Incorporation of S100 and CD1a is helpful in diagnoses of RDD and differentiating it from other benign histiocytosis." (PMID 23738161, 2013). "Therefore, the first attempt to characterize the skin biopsy fragments was made, a diagnosis of Lanherhans Cells Histiocytosis was discussed, based on CD68+++, CD 45+, MPO+, CD1a-, S-100-, desmin -, MY14-." (PMID 29450403, 2017). "It contributed in excluding aspiration, infection, and histiocytosis as there were no lipid laden macrophages, all cultures and viral studies were negative, and CD1a coloration was negative." (PMID 24954625, 2014). "Additionally, we noted that the presence of CD1a-positive cells in primary cultures of sl-pHCs was not correlated with BRAF mutation, histiocytosis type, or disease outcome." (PMID 38342891, 2024).